IL13 (interleukin 13)
Diseases named in the same sentence as IL13 in open-access papers (continued):
Sharing a sentence is not in itself a finding about the gene and the disease.
psoriasis (continued). "Eosinophils are involved in type II immune response, which is related to T helper 2 cells and various interleukins (including IL-4, IL-5, IL-9, IL-13, IL-31, and IL-33, among others), differing from the IL-17/23 axis of psoriasis." (PMID 36865550, 2023). "The anti-inflammatory potential of IL-13 has been therapeutically investigated in a variety of pathologies, including psoriasis, arthritis, and Alzheimer’s disease." (PMID 38035087, 2023). "There is evidence supporting a significant correlation between IL-13 and psoriasis/ psoriatic arthritis." (PMID 36314037, 2022). "Anti-inflammatory roles of IL-4 and IL-13 are well documented in the pathogenesis of psoriasis, type I diabetes, and experimental autoimmune encephalomyelitis (EAE)—the animal model of multiple sclerosis." (PMID 34831223, 2021). "The most commonly involved inflammatory markers observed in the pathogenesis of both depression and Psoriasis are IL-6, IL-17, IL-13, IL-23, IL-10, IL-1β, and type A cytokines (TNF-α, IL-2, INF-γ) through Th1 and Th17 lymphocytes mediated processes." (PMID 34183985, 2021). "We found one crossover locus of IL13 for psoriasis, two crossover loci BLK and ITGAM/ITGAX genes for SLE and four crossover loci near TFPI, CYP2A1, PECAM1, and CXCL12 for CAD data set." (PMID 32779262, 2020). "An excellent therapeutic response to biologics indicates a pivotal pathogenic role of interleukin (IL)-4/IL-13 signaling in AD and the tumor necrosis factor (TNF)-α/IL-23/IL-17A axis in psoriasis." (PMID 31683543, 2019). "The decrease in CD4+ T effector-derived IL-13 seen in all subtypes of psoriasis is consistent with previous studies and suggests a shift in the Th1-Th2 axis." (PMID 30054515, 2018). "All three psoriasis subtypes had significantly lower IL-13 from CD4+ T effector cells compared to healthy control skin." (PMID 30054515, 2018). "To validate the data obtained by microarray, we performed qRT-PCR and included AD like conditions (IL-4 and IL-13 treatment) as well as psoriasis like conditions (IL-22, OSM, IL-17, and TNFα treatment) in our experimental setup." (PMID 28928464, 2017). "Our data clearly demonstrate that TWEAK is important for maximal disease in two well-established models of AD and psoriasis that display the Th2 (IL-13) or Th17 (IL-17) phenotypes." (PMID 28530223, 2017). "A large number of studies have established that there were lesion-related inflammatory cytokines produced by CD8+ in tissues of patients with psoriasis, particularly IL-13, IL-17, IL-22." (PMID 28881648, 2017). "The 3D skin equivalents were incubated, up on day four for the following three days under AD like conditions (IL-4 and IL-13), psoriasis like conditions (IL-22, OSM, IL-17, and TNFα) or left untreated." (PMID 28928464, 2017). "Initial causative research has identified strong association between psoriasis and the interleukin genes (IL4, IL10, IL12B, IL13, and IL23R) in the northern European from US and UK." (PMID 24971308, 2014). "We genotyped seven single-nucleotide polymorphisms (SNPs) in candidate genes of six ILs: IL4, IL10, IL12B, IL13, IL15, and IL23R, which have been shown in the literature to be associated with psoriasis in other ethnic groups." (PMID 24971308, 2014). "Both exhibited opposing effects in AD and psoriasis, and localized to the gene IL13 (rs1295685, P = 4.94E−09 and rs20541, P = 1.786E−08)." (PMID 23886662, 2013). "In these models, we finally analyzed the effects of the change from IL-17 (Th17, psoriasis) to IL-4/IL-13 (Th2, AD), in the same cytokine background (TNFα and IL-22)." (PMID 23193414, 2012). "This case of lebrikizumab-induced psoriasis in a patient with AD supports the concept that inhibition of IL-13, like IL-4, may play a role in shifting the immune response toward the Th17 axis, precipitating psoriatic disease." (PMID 41542312, 2026).
psoriasis (continued). "Psoriasis has previously been described in an AD patient following treatment with tralokinumab and now in our patient following treatment with lebrikizumab, with both drugs sharing a similar mechanism of action by selectively inhibiting IL-13." (PMID 41542312, 2026). "Here, we present a case of paradoxical psoriasis following treatment with lebrikizumab in a patient with AD, providing new insight into the role that selective IL-13 inhibition may play in this paradoxical skin reaction." (PMID 41542312, 2026). "IL-17 and IFN-γ, which play a critical role in the pathogenesis of psoriasis, significantly enhanced the R7-triggered IL-6 secretion, and the Th2 cytokines IL-4 and IL-13, which play a critical role in the pathogenesis of AD, tended to enhance the stimulatory effect of R7 on IL-6 secretion." (PMID 40461723, 2025). "While the immunologic role of IL-13 in psoriasis remains less clearly defined than that of Th1 or Th17 cytokines, IL-13 is known to exert anti-inflammatory and tissue-regulatory effects, including suppression of proinflammatory mediators and promotion of epithelial repair." (PMID 40650209, 2025). "Incorporating IL-13, IL-18, and their ratio into clinical algorithms may facilitate precision-guided biologic therapy in psoriasis." (PMID 40650209, 2025). "Furthermore, new‐onset psoriasis can occur during anti‐IL‐4 receptor alpha treatment (dupilumab), suggesting a suppressive role mediated by the IL‐4/IL‐13 axis." (PMID 40926620, 2025). "Additionally, serum IL-13 levels and IL-13-related cytokine ratios (e.g., IFN-γ/IL-13, IL-17A/IL-13) have been associated with clinical responses to biologic therapies in psoriasis." (PMID 40650209, 2025). "Psoriasis was traditionally viewed as a Th1-mediated disorder, largely due to elevated IFN-γ production by CD4+ T cells within psoriatic lesions and minimal expression of Th2-associated cytokines such as IL-4, IL-5, and IL-13." (PMID 41226338, 2025). "The proposed mechanism involves a shift in immune balance by suppressing the Th2 pathway via IL-4/IL-13 blockade; dupilumab may unmask latent Th1/Th17-driven conditions, such as psoriasis." (PMID 41281095, 2025). "In psoriasis, pruritus involves Substance P, IL-2, calcitonin gene-related peptide (CGRP), μ-opioid receptors (OPRM), and κ-opioid receptors (OPRK), while in AD pruritus is linked to thymic stromal lymphopoietin (TSLP), CGRP, IL-4, IL-13, and IL-31." (PMID 39859462, 2025). "In the case of the psoriasis model, a TH17-associated cytokine cocktail (IL-17A and IL-22) was used, and in the case of the AD model, a TH2-associated cytokine cocktail (IL-4, IL-5 and IL-13) was used." (PMID 38251799, 2024). "The mechanisms of different biologics on IL-4 and IL-13 levels in individual patients with psoriasis remain unclear and need to be elucidated in the future." (PMID 38791078, 2024). "However, in psoriasis, IL-36 induces the activation of the IL13/IL17A axis at the skin, contributing to the inflammatory process and, thus, to the severity of the disease." (PMID 37550362, 2023). "The role of other cytokines in psoriasis is often controversial, including IL-4, IL-10, and IL-13." (PMID 36618400, 2022). "The dominance of IL-13 pathways in AD is presented in Reactome pathway enrichment, which is consistent with the recent study (11 In summary, psoriasis has discernable auto-immunological activations, while AD has increased presence of dermal response to stimulus." (PMID 35874668, 2022). "The JAK/STAT signaling and spleen tyrosine kinase (SYK) pathways are implicated in numerous autoimmune and inflammatory diseases (e.g. AD, psoriasis, alopecia areata), modulating a range of immune responses, including the Th2 (IL-4, IL-13, CCL18), Th1 (IFNγ), and Th17/Th22 (CCL20, S100As) pathways." (PMID 33329590, 2020). "We also tested whether TWEAK might function in synergy with the signature cytokines of AD and psoriasis, IL-13 and IL-17A, whose receptors are also expressed on keratinocytes." (PMID 28530223, 2017).
psoriasis (continued). "3D skin equivalents made of GATA3 shRNA transduced cells showed the tendency to express less FLG when compared to the respective control 3D skin equivalent under all investigated conditions (ns, AD-like (IL-4 and IL-13), and psoriasis-like (IL-22, OSM, IL-17, and TNFα) conditions)." (PMID 28928464, 2017). "Subsequent studies in Canadian and UK populations confirmed these findings and reported variants of IL13 to be significantly associated with PsA but not with psoriasis." (PMID 26255310, 2016). "The index SNP in this PsA study is statistically independent of the IL13 psoriasis-associated variant." (PMID 25651891, 2015). "However, with respect to two other psoriasis susceptibility loci (rs1008953/SDC4 and rs2082412/IL12B), risk alleles were enriched in subjects with IL-13-weak patterns (Cliff's delta ≥0.25; P≤0.045; FDR-adjusted P≤0.40)." (PMID 22479649, 2012). "Interestingly, the replacement of IL-4 and IL-13 by IL-17 from this cocktail is able to mimic in vitro a “psoriasis-like” status on keratinocytes." (PMID 23193414, 2012). "As proposed previously, an effective therapeutic strategy in psoriasis may not only involve suppression of Th1 and Th17 responses but also aim to restore immune balance by enhancing Th2-mediated pathways, particularly through cytokines such as IL-4 and IL-13." (PMID 40650209, 2025). "One report, for instance, has commented that intensity of immunohistochemical IL-13Rα1 staining tends to be stronger in psoriasis lesions that are larger in size, which potentially, may reflect differential activation of IL-13-sensitive pathways across stages of plaque development." (PMID 22479649, 2012). "Several SNPs used as IVs in the psoriasis MR analyses are located in or near genes with known immunological and inflammatory functions relevant to both diseases, such as IL23R, IL13, TRIM27, HLA-A, HLA-B, and TNFAIP3." (PMID 41465162, 2025). "The biomarkers IFN-γ, IL-13, IFN-γ/IL4, IFN-γ/IL13, IL-17A/IL-4, and IL-17A/IL-13 are representative of the effectiveness of psoriasis treatment." (PMID 38791078, 2024). "AD models can be generated by adding TH2 cytokines such as IL-4 and IL-13, and TNF-α, whereas psoriasis models are induced by treating skin models with cytokine cocktails based on IL-17, IL-22 and TNF-α." (PMID 38251799, 2024). "This interruption in cytokine signaling effectively reduces the inflammatory response mediated by cytokines such as IL-4, IL-13, IL-31, IL-22, and IFN-γ, which are critical in conditions like AD, psoriasis, and alopecia areata (AA)." (PMID 39610670, 2024). "The markers IFN-γ, IL-13, IFN-γ/IL13, IL-17A/IL-13, IFN-γ/IL4, and IL-17A/IL-4 are representative of predicting the efficacy of psoriasis treatment." (PMID 38791078, 2024). "As cytokines represent important drivers of tissue inflammation in ncISD, we examined the expression of the major effector cytokines driving the common ncISD LP, AD, and psoriasis namely IFNG, IL13 and IL17A, respectively, in spatial resolution." (PMID 36513651, 2022). "The median number of transcript-positive cells per section for IFNG, IL13, and IL17A mRNA were 83, 4 and 11 for LP, AD, and psoriasis, respectively, thus confirming our observations from the ST analysis." (PMID 36513651, 2022). "IFNG transcripts were mostly expressed in lesional LP (median/section:4), IL13 (median/section:1.5) and IL17A (median/section:9) in AD and psoriasis, respectively, with an emphasized expression in upper skin layers." (PMID 36513651, 2022). "A selective AHR agonist, tapinarof is currently being studied because this medicinal agent improves both psoriasis and AD in which different pathomechanisms operate (the TNF-α/IL-23/IL-17 axis in psoriasis and IL-4/IL-13 signaling in AD)." (PMID 31683543, 2019). "Gene interaction analyses highlighted IFNG, IL4, IL10, MMP9 and TIMP1 in IBD; IL10, IL13 and PTGS2 in psoriasis; IL8, IL10 and PTGS2 in RA." (PMID 20444268, 2010).
psoriasis (continued). "Additionally, we identified distinct T cell expression patterns across disease states, including characteristic expression of IL13 and IL22 in AD, IL17 family genes in psoriasis, and IFNG in granuloma annulare (GA)." (PMID 40537825, 2025). "Patients received treatment with anti-IL-4RA or anti-IL-13 (anti-Th2), anti-IL23 or anti-IL-17A (Anti-Th17), or JAK1 inhibitors (with the ability to target Th1) based on their diagnosis of AD, psoriasis, or LP established by clinical and histopathology criteria." (PMID 39695162, 2024). "Results indicated that IDG and DXM significantly inhibited the expression of IL-6, IL-17A, MCP-1, and TNF-α in psoriasis-like lesions, with all findings reaching statistical significance, while the effect on IL-13 was not statistically significant." (PMID 39465158, 2024). "We observe that single transcripts of disease-promoting cytokines, namely IFNG for LP, IL13 for AD, and, IL17A for psoriasis initiate localized amplification cascades of specific inflammatory responder genes that collectively represent hallmarks of the respective disease pathogenesis." (PMID 36513651, 2022). "Although the cytokines such as IL-4, IL-10, and IL-13 play a relevant role in the pathophysiology of psoriasis, the corresponding inhibitors in clinical trials have not yet achieved the expected efficacy." (PMID 36618400, 2022). "The current clinical treatment of psoriasis completely involves topical drugs, including vitamin D3 analogues, topical corticosteroids, calcineurin inhibitors, keratolytics, and biologics that inhibit TNF-α, IL-12, IL-13, IL-17, and IL-23." (PMID 35813890, 2022). "Other cytokines and receptors with low expression levels and consistently minimal or no changes in psoriasis (IL13, TNFRSF11A, TNFRSF11B, and TNFSF11) showed similar results across all three platforms." (PMID 23308107, 2013). "Initial studies showed that IL-13 mRNA levels do not differ significantly between lesional and non-lesional skin samples from psoriasis patients." (PMID 22479649, 2012). "Paradoxical psoriasis following treatment with IL-4/IL-13 inhibitors like dupilumab, but historically not with selective IL-13 inhibitors, has led to the hypothesis that IL-4 blockade is the key driver of this phenomenon." (PMID 41542312, 2026). "In psoriasis patients, we expected to see primarily IFNγ signatures rather than IL‐4 + IL‐13." (PMID 40926620, 2025). "While Th2 cytokines such as IL-4, IL-13, IL-33, and TSLP dominated the inflammatory landscape in AD and bullous pemphigoid, Th1 and Th17 immune responses, primarily mediated by IFN-γ and IL-17, characterized psoriasis, lichen planus, and specific forms of GvHD." (PMID 41479908, 2025). "Additionally, IDG was shown to inhibit the expression of IL-6, IL-13, IL-17A, TNF-α, and MCP-1, suggesting that IDG may exert its therapeutic effects on psoriasis through its anti-inflammatory properties." (PMID 39465158, 2024). "Interestingly, Th2 cytokines such as IL-4 and IL-13, expressed by MCs, and suggested as signalling bridges between immune sense and nerve fibres, were not modulated in MCs in psoriasis." (PMID 37681909, 2023). "The role of IL-13 in the initiation or maintenance of psoriasis lesions is not yet clear." (PMID 22479649, 2012).
allergic rhinitis (86 papers, 2010 to 2026). Inflammation of the nasal mucous membranes caused by an IgE-mediated response to external allergens. "Allergic rhinitis is associated with IL-4 and IL-13 polymorphism, and dual blockade of IL-4 and IL-13 with dupilumab, an IL-4Rα antibody, is required to inhibit type 2 inflammation such as AR." (PMID 38629073, 2024). "A molecular genetic study of the IL-13 R130Q (rs20541) locus polymorphism showed a significantly increased rate of the GA genotype and A allele in patients with allergic rhinitis, in contrast to healthy people in the control group." (PMID 35629280, 2022). "According to the cytokine profile in the preseasonal ASIT regimen, the development of allergic rhinitis was predominantly associated with IL-5 and IL-13 production, and bronchial asthma with IL-4, IL-5, IL-13, and TNF-α, which is consistent with other reports." (PMID 36439113, 2022). "Interleukin (IL)-13-associated inflammatory response is important for the pathogenesis of allergic rhinitis (AR)." (PMID 34607526, 2021). "A number of studies have shown that the IL-13 -1112 gene polymorphism is associated with a variety of diseases, including type 2 diabetes, chronic obstructive pulmonary disease, allergic rhinitis, inflammatory bowel disease and colorectal cancer." (PMID 29415708, 2018). "With SHP-1 deficiency, mev mice display an allergic rhinitis-like phenotype, which is largely dependent on Th2 cytokines (IL-4 and IL-13) and eotaxin." (PMID 25090641, 2014). "Six previous studies have examined the relationships between single nucleotide polymorphisms (SNPs) in the IL13 gene and allergic rhinitis, but the results have been inconsistent." (PMID 22023794, 2011). "Studies conducted on allergic rhinitis showed that there is an association of IL-4 with significant increase in IL-13 and TNF α." (PMID 20616938, 2010). "Besides, the polymorphisms of IL-13 involved in some other diseases, such as eczema, allergic rhinitis." (PMID 23663500, 2013). "IL-13 may be associated with allergic rhinitis when the individuals are provoked with an allergen." (PMID 22230487, 2012). "In PBMCs from allergic rhinitis patients, 6B12 treatment reduced secretion of IL-5 and IL-13, a key cytokine involved in the pathogenesis of allergic rhinitis." (PMID 40078995, 2025). "In an experimental study in rats with allergic rhinitis, hesperidin significantly reduced the levels of IgE, IL-5, and IL-13 and modulated the oxidative balance." (PMID 41001345, 2025). "A study reported that reflux ethanolic extracts of LE significantly reduced the levels of IL-4 and IL-13 in nasal lavage fluid obtained from murine models of allergic rhinitis." (PMID 41560747, 2025). "After different administrations, CCR3mAb i.p. group had increased trends in Th1 cytokines (IFN-γ and IL-2) compared to allergic rhinitis mice, with statistical significance; and decreased trends in Th2 cytokines (IL-4, IL-5, and IL-13)." (PMID 38212473, 2024). "There is evidence that T cell-mediated Th2 cytokines including IL-4, IL-5, and IL-13 are elevated in patients with allergic rhinitis, and can regulate eosinophil growth and differentiation." (PMID 35831673, 2023). "HCP5/miR-16/ATXN2L are associated with regulatory T-cell differentiation and function, and regulated IL-13-induced inflammatory cytokine and mucus production in allergic rhinitis." (PMID 35122570, 2022). "The expression of IL-4, IL-5, and IL-13 mRNA was significantly higher in mice with OVA-induced allergic rhinitis than in the control group; however, they were significantly lower in mice treated additionally with LE_R or CIC." (PMID 36142314, 2022). "In an allergic rhinitis mouse model, SHEDs inhibited the Th2 immune response by downregulating IL-4, IL-5, and IL-13 levels in spleen lymphocytes and decreasing the production of serum IgE and IgG1." (PMID 35909660, 2022). "In a mouse model of allergic rhinitis, gallic acid decreased the IL-4, IL-13, and IL-17 levels in mouse model of allergic rhinitis." (PMID 36235070, 2022).